ESR1 (estrogen receptor 1)
Diseases named in the same sentence as ESR1 in open-access papers (continued):
Sharing a sentence is not in itself a finding about the gene and the disease.
cancer (continued). "Similarly, ESR1 expression is higher when ESR1 is mutated in BRCA, CESC, and UCEC, which are all hormone receptor-related cancer types." (PMID 29617662, 2018). "We detected ESR1 fusions in 16 samples from five different cancer types (9 samples from BRCA)." (PMID 29617662, 2018). "In contrast, AR is highly expressed in HER2-positive or ESR1/PGR-positive cancers (> 95%)." (PMID 30279965, 2018). "This suggests that ESR1, oestrogen receptor alpha, may play a significant role across the hallmarks of cancer, and de-repression by reduction of its miRNA-mediated repression may play a role in cancer phenotype, and ultimately, oncogenesis." (PMID 30531873, 2018). "In Case M50 plasma was collected and cfDNA was analyzed, but did not have the E380Q ESR1 mutation probably because the E380Q ESR1 mutation in ttDNA was in a subpopulation of cancer cells." (PMID 29166868, 2017). "Further studies are required to confirm the efficacy of CDK4/6 inhibitors in ESR1 mutant cancer." (PMID 28623955, 2017). "Nonetheless, ESR1 mutants treated with fulvestrant had modestly worse PFS than wild-type cancers." (PMID 28361033, 2017). "More potent receptor degraders may have the potential to further improve results in comparison with fulvestrant in ESR1 mutant cancers, and a number of such therapies are in early clinical development." (PMID 28361033, 2017). "Furthermore, the SNVs in CTNNB1, PIK3CA, PTEN and ESR1 were annotated in COSMIC, the catalogue of somatic mutations in cancer." (PMID 28103826, 2017). "Furthermore, impacts on pathways WILLIAMS_ESR1_TARGETS_DN and FRASOR_RESPONSE_TO_ESTRADIOL_UP point towards effects related to estrogen receptor-alpha (ERα) signaling which is important in several cancers." (PMID 27887572, 2016). "Negative correlation between ESR1 and HLA and positive correlation between interferon-associated and HLA gene expression were also confirmed in Cancer Cell Line Encyclopedia (CCLE) data." (PMID 27121061, 2016). "Interestingly, qPCR also showed that GABRP expression was down-regulated (67.8 %, 103 in 152, P < 0.0001) and ESR1 expression was up-regulated (53.3 %, 81 in 152, P = 0.008) in these cancer tissues compared with their corresponding adjacent normal tissues." (PMID 25990390, 2015). "Thus, malignant tumors showed significantly lower ERα (ESR1) and PGR gene expression than normal mammary tissues (p = 0.017 and p = 0.002, respectively)." (PMID 26370564, 2015). "We found no human cancer-associated polymorphisms in close proximity to the canine ESR1 exon 2 SNP (rs21960513)." (PMID 23574728, 2013). "Some of these were supported by ESR1 ChIP-seq peaks derived from primary cancer samples but this is likely limited by the small number of binding sites in common between samples and the relatively differentiated nature of the chromatin architecture compared with cell lines." (PMID 24171864, 2013). "In addition, transcription factors E2F1 and ESR1 are involved in the signaling pathways, which are important transcription factors and therapeutic targets in different types of cancer, including BC." (PMID 24040069, 2013). "Of note, the 5 shared candidate cancer genes of tumors 05 and 09 (Pten, Fas, Esr1, Abl2, Lrp1b) were independently obtained in both tumors with similar average read frequencies, confirming the robustness of our sequencing method to identify clonal expansion of insertions." (PMID 23940809, 2013). "Except for c6orf97, a 127 kbp long open reading frame located upstream of the esr1 gene, the remaining ten hERα targets have not yet been associated to estrogen signaling or cancer activity." (PMID 19689805, 2009). "Several key biological pathways are enriched for cancer-specific sets of isoTWAS-prioritized genes, including cell cycle and mitosis regulation, DNA and RNA binding, immune pathways, as well as downstream targets of cancer-relevant transcription factors like ESR1, RUNX2, and YY1." (PMID 40775447, 2025).
cancer (continued). "We found that this strategy results in modest improvement in outcomes, and certain subgroups (older patients, no chemotherapy, absence of any cancer involvement of the organs, certain mutations like ESR1 mutations, and non-use of palbociclib as the CDK4/6i) did better." (PMID 40427107, 2025). "Moreover, ESR1 upregulation makes BC cells more prone to estrogen uptake which may lead to the increased growth and proliferation of cancer cells." (PMID 37900178, 2023). "Moreover, Patel and colleagues have shown that elacestrant exhibits anti-cancer activity in the cells resistant to all CDK4 and 6 inhibitors approved to date, namely palbociclib, abemaciclib, and ribociclib in both wild-type and mutated ESR1." (PMID 37835383, 2023). "The presence of ESR1 mutations acquired during prior endocrine therapies was correlated with improved efficacy for elacestrant (12 month PFS: 26.8% vs 8.2%), consistent with ESR1 mutations being a surrogate marker for cancers with preserved dependence on ER signaling." (PMID 37318638, 2023). "An ERα-36 variant, encoded by ESR1 exons #2–6 and an additional exon downstream of the ESR1 gene, encoding a protein expressing the DNA-binding domain, a truncated LBD and a partial dimerization domain has been described in a variety of cancer models including tamoxifen-resistant breast cancers." (PMID 35999225, 2022). "Notably, hsa-miR-18a and -18b are known to regulate ESR1 expression in cancer tissues." (PMID 35682668, 2022). "The seven prevalent ‘candidate genes’ (ADAM10, ADAM17, AKT1, CTNNB1, ESR1, FGFR1, PIK3CA) showed direct associations with enriched terms under the categories of ‘Neurodegenerative disorders’, ‘Neurodevelopmental diseases’, ‘CNS tumour/cancer’ and ‘Cellular Signaling pathways’." (PMID 36229517, 2022). "Therefore, while miR-1260 appears to function in a non-ESR1 regulatory network, its perturbation in response to cancer progression or drug treatment may play a significant role in regulation of the CYPs." (PMID 36059981, 2022). "Besides one variant with no known pathogenic function (P-123), ESR1 variants associated with hormone-therapy resistance were restricted to the HR-positive cancers and more frequent in patients with liver metastases." (PMID 34504096, 2021). "Thus, to treat cancers harboring ESR1 LBD mutants, it will be necessary to develop combined treatments composed of SERD/SERM associated with other compounds, such as THZ1, a CDK7 inhibitor, making it possible to fight against the metastatic propensity of these mutants." (PMID 33451133, 2021). "In this study we evaluated a number of cancer variants that are associated with resistance to endocrine therapy alone or in combination with or without PI3K/AKT/mTOR or CDK4/6 inhibitors, such as PTEN gene copy number loss and ESR1 activating mutations and copy number gain." (PMID 34471951, 2021). "Similarly, Esr1 KO females had more carcinomas than WT females (95% vs 70%)." (PMID 34068249, 2021). "It should be noted that the majority of the samples in this data set came from patients with stage 4 cancer (n = 81 of 140), suggesting that the prognostic value of ESR1 expression as a marker of LSCC aggression may exist independent of any association with late-stage cancer." (PMID 32144339, 2020). "Furthermore, ESR1-responsive enhancer hypomethylation is critical in the transition from normal epithelial cells to endocrine-responsive luminal-like BC, supporting the concept that dynamic epigenetic variations are pivotal in cancer evolution." (PMID 33072577, 2020). "Interestingly, we also observed ESR1 as a key hub gene in the cancer network." (PMID 31620367, 2019). "Furthermore, since the signature was consistently negatively correlated with the ESR1 module in all three cancers, and high signature scores led to poor outcomes, we believe the signature also models the poor outcomes associated with increased ER pathway activity in patients." (PMID 31217513, 2019).
cancer (continued). "Finally, we demonstrated that psychiatric disorders may share the same signaling pathways with cancers, involving ESR1, BCL2 and MAPK3." (PMID 27917343, 2016). "Therefore, newly developed mixed SERM/SERDs and SERDs with improved pharmacokinetics and oral bioavailability over fulvestrant, such as AZ9496, bazedoxifene, GDC910, and RAD1901, should be particularly effective against cancers expressing the Y537S and D538G ESR1 mutants." (PMID 26836308, 2016). "However, here we propose more specifically that the progressive suppression of ESR1 activity from early hyperplastic tissue to cancer is mediated by PB chronic exposure and is one of the mechanisms underlying PB-mediated liver tumor promotion due to negative regulation of tissue morphogenesis." (PMID 24464994, 2014). "These genes include those mutated in other cancer types and bound with HCV proteins (e.g. PIK3R1 and EP300), genes interfacing with alternative partner groups (e.g. YWHAZ), and genes manifesting both differential co-expression and differential expression (e.g. ESR1)." (PMID 24564909, 2013). "For example, to access information about the BRCA1 (breast cancer 1, early onset), GSTP1 (glutathione S-transferase pi) and ESR1 (estrogen receptor 1) gene methylation profile across various types of cancer, a user could input BRCA1, GSTP1, ESR1 as search terms separated by line breaks." (PMID 22168213, 2011). "We also found by Ualcan analysis of the TCGA database that the expression of ESR1 and KRT19 in different cancer stages, races, genders, age groups, histological subtypes, and lymph node metastasis status were significantly different in THCA (All P < 0.05)." (PMID 39453570, 2025). "In contrast, seven out of ten anti-AD core targets (PTGS2, MAPK1, MAPK3, JUN, ESR1, IL6, and PIK3CA) followed the pathways in cancer." (PMID 40179089, 2025). "Mechanistic studies revealed FS targets key molecules (STAT3, EGFR, ESR1, PTGS2, NF-κB1, and JUN), modulating PI3K-Akt, MAPK and cancer-related pathways." (PMID 40649400, 2025). "Protein–protein interaction networks identified hub genes for each cancer type, with key shared targets including EGFR, ESR1, PTGS2, and STAT3." (PMID 41155677, 2025). "Critical targets such as TNF, EGFR, ESR1, HIF1A, HSP90AA1, and SRC were involved in pathways including chemical carcinogenesis, PI3K‐Akt signaling, proteoglycans in cancer, receptor activation in chemical carcinogenesis, and immunomodulation." (PMID 40144560, 2025). "Based on this analysis, the genes STAT3, MYC, CTNNB1, ESR1, JUN, and BRCA1 emerged as pivotal genes, indicating their significant impact on each cancer type in response to radiation exposure." (PMID 41186627, 2025). "It has been shown that ESR1 and PGR were highly expressed in MCF7, T47D, and MDA-MB-361 metastatic cell lines, suggesting that these cancer cells represent models of estrogen- and progesterone-dependent cancers." (PMID 38339272, 2024). "Topological analysis of the PPI network, using the STRING database and Cytoscape 3.10.2, identified seven core targets crucial in cancer pathways: CYP3A4, PIK3R1, PIK3CD, ESR1, AKR1C3, EGFR, and CYP19A1." (PMID 39204124, 2024).
cancer (continued). "Pathway analyses were performed among different ESR1/EERES groups to identify genes that correlate with endocrine resistance, which are validated using Cancer Cell Line Encyclopedia gene expression and Genomics of Drug Sensitivity in Cancer data." (PMID 38582811, 2024). "First, we compared the fold change in expression of the ER-related receptors ESR1, ESR2, ESRRA, ESRRB, ESRRG, and GPER1 in the four female cancers." (PMID 38582811, 2024). "Network pharmacology with the relevant databases and software was used to predict potential targets like CASP3, SRC, ESR1 and JAK2 and pathways such as PI3K-Akt, proteoglycans and focal adhesion in cancer." (PMID 38675723, 2024). "The differential expression of PIK3R1, AKR1C3, EGFR, ESR1, PIK3CD, CYP3A4, and CYP19A1 across various cancer types and stages illuminates their potential as biomarkers for cancer progression and prognosis." (PMID 39204124, 2024). "Based on the drug information, 29 sex-biased mRNAs were drug-targeted genes and six (CD38, PGR, ESR1, GABRP, F3, PRKCB) of them were targeted by cancer therapeutic drugs." (PMID 39175079, 2024). "There is insufficient research on the PTGS2, CASP3, ESR1, and BCL2 targets in cancer-induced fatigue." (PMID 39564104, 2024). "Genes such as PARP1, NAMPT, AIMP2, MCL1, and TOMM20 exhibited widespread amplifications of CNVs in multiple cancers, while genes like RNF146, GPX4, ESR1, CUL4A, and PTEN showed widespread deletions." (PMID 38499384, 2024). "The expression patterns of estrogen and its related proteins, including estrogen-related receptor alpha (ESRRA), ESRRG, ER-alpha (ESR1), and ER-beta (ESR2), were examined in the HPA in different types of cancers." (PMID 37240447, 2023). "For example, this is the case for estrogen response genes (e.g., ESTROGEN_RESPONSE_EARLY) specifically enriched in BRCA, with ESR1 and PGR highly correlated with MAPT in this cancer type." (PMID 37730697, 2023). "We also observed a positive significant (p < 0.05) correlation between the ESR1 gene expression level and NLGN4X expression in BRCA-Her2 and BRCA-LumB cancer patients and MBP expression in BRCA-LumA and -LumB patients." (PMID 38137332, 2023). "On the other hand, the ESR1 and MBP correlation was positive in BRCA-LumA and Lum-B cancer patients." (PMID 38137332, 2023). "We obtained the following correlation values (and statistical significances) between ESR1 and AP2A1 in the cancer samples: COR(PTA) = 0.9607 (p-val = 0.03093), COR(PTB) = 0.970449 (p-val = 0.02955), and COR(CWM) = 0.958562 (p-val = 0.04144)." (PMID 38132440, 2023). "Note also that important genes distinguishing between cancer subtypes, e.g., for breast cancer, like ERBB2 (HER2), ESR1 (ER), and two forms of membrane component of PR, PGRMC1 and PGRMC2, survived shambhalization." (PMID 37745690, 2023). "AKT1, EGFR, SRC, ESR1, and PTGS2 are the top five targets in the PPI network, and they were reported as critical regulatory factors in cancer metastasis and EMT." (PMID 35942366, 2022). "ESR1 deems to share CTNNB1-54 and AKT1-55 mediated signalling pathways to accelerate cancer and neurodegeneration, respectively." (PMID 36229517, 2022). "The targets in the cancer pathways (SRC, EGFR, ESR1, PTGS2, and APP) were used for molecular docking analysis with all active compounds." (PMID 36561345, 2022).
cancer (continued). "These clinical characteristics may be secondary to activation of the EMT in ERα negative cancers, as low mRNA expression of the gene encoding ERα, ESR1, has been associated with high expression of the EMT transcription factors SNAIL, SLUG, TWIST1, ZEB1, and ZEB2." (PMID 36052252, 2022). "There were also differences in the types and frequencies of genetic alterations in ESR1, ESR2, and PGR in multiple cancer types." (PMID 34322374, 2021). "Our results revealed genetic alterations in ESR1, ESR2, and PGR in multiple cancer types, including amplification, fusion, deep deletion, missense mutation, and truncating mutation." (PMID 34322374, 2021). "ESR1 Cr values strongly positively correlated with ESR2 Cr only in unchanged tissue and was moderately correlated with both PELP1 Cr and SRC Cr in cancer affected tissue." (PMID 34207568, 2021). "ESR1-201, ESR1-202, ESR2-004, ESR2-005 and PGR-001 were mostly commonly used transcribed isoforms in different cancer types." (PMID 34322374, 2021). "To assess the relevance of ESR1, ESR2, and PGR with immune system that plays critical roles in cancer progression, we first compared their co-expression with the abundance of immunomodulators." (PMID 34322374, 2021). "In the Cancer Dependency Map (depmap.org), the top FOXA1 co-dependencies from the CRISPR screen data (AVANA) by Pearson correlation are SPDEF followed by ESR1 (estrogen receptor alpha) and TRPS1, underscoring the critical interplay of FOXA1 and ESR134." (PMID 33980863, 2021). "ESR1, TOR1AIP1, STAT1, COL1A1 were identified as high expression, while EGFR, AR, GATA2 were identified as a low expression in both cancer types." (PMID 33907495, 2021). "Together, the potential roles of ESR1, ESR2 and PGR in cancer are likely in an immune system-dependent manner." (PMID 34322374, 2021). "The genes selected included epithelial (KRT5, CDH1, EpCAM), mensenchymal (VIM, SNAI1, TWIST), stem (ALDH1A1, PROM1), breast specific (ESR1, PALB2) and other genes related to cell cycle or other cancer pathways (CCND1, CTNNB1, Ki67, etc.)." (PMID 34071445, 2021). "Src axis couples ESR1 with PELP1 and depletion of c-Src inhibited the growth of therapy resistant cancers in in vitro models." (PMID 34207568, 2021). "To explore the expression of ESR1, ESR2 and PGR in pan-cancer, we analyzed their mRNA levels via GEPIA2." (PMID 34322374, 2021). "Generally, the results of this study indicated that ESR1, ESR2, and PGR can be regarded as predictive and prognostic biomarkers across different cancer types." (PMID 34322374, 2021). "To investigate the distribution of ESR1, ESR2, and PGR isoforms in pan-cancer, we compared their expression levels via GEPIA2." (PMID 34322374, 2021). "Thus, suppression of ESR1 gene activation may be used for anti-cancer strategy." (PMID 34592904, 2021). "To investigate the potential roles of ESR1, ESR2, and PGR in prognosis, we analyzed the correlation of their expression with pan-cancer survival." (PMID 34322374, 2021). "Several important metastasis- and cancer-related pathways were enriched, including cell cycle regulation, angiogenesis, EMT, and Wnt, TGF-β and ESR1-mediated signaling." (PMID 33784351, 2021). "ESR1-depleted recurrences harbored shared transcriptional remodeling events including upregulation of PROM1 and other basal cancer markers." (PMID 33407744, 2021). "We then compared ESR1 and ESR2 mRNA expression levels difference in 23 cancer types with both tumors and adjacent normal tissues." (PMID 32536040, 2020). "As in cancer cells, KDM1A binds to AR and ESR1 in trophoblast cells, and therefore is thought to play a role in regulating AR and ESR1 signaling in the placenta." (PMID 33029224, 2020).